HACE1 (HECT domain and ankyrin repeat containing E3 ubiquitin protein ligase 1)
Diseases named in the same sentence as HACE1 in open-access papers (continued):
Sharing a sentence is not in itself a finding about the gene and the disease.
Wilms tumor (10 papers, 2012 to 2025). An embryonal neoplasm characterized by the presence of epithelial, mesenchymal, and blastema components. "The hypermethylation of CpG29 and CpG177 islands upstream of the HACE1 transcription start site (TSS) is associated with its low expression level was reported in human Wilms tumor." (PMID 40948788, 2025). "A prime example is HECT domain and ankyrin repeat containing E3 ubiquitin protein ligase 1 (HACE1), which was first identified in 2004 as a tumor suppressor caused by chromosomal translocation that leads to sporadic Wilms tumor with decreased HACE1 expression." (PMID 33435370, 2021). "Besides being genetically linked to Wilms tumor formation, HACE1 has also been reported to play a role in the onset of liver, lymphoma, osteosarcoma, breast and colorectal cancers." (PMID 33435370, 2021). "Their data implicated that low expression of HACE1 was associated with sporadic Wilms’ tumor." (PMID 34707697, 2012). "One child with unilateral Wilms’ tumor and a truncated HACE1 mutation was identified." (PMID 34707697, 2012). "However, HACE1 mutations are rare and therefore can only make a small contribution to Wilms’ tumor incidence." (PMID 34707697, 2012). "It was concluded that constitutional disruption of HACE1 likely predisposes Wilms’ tumor." (PMID 34707697, 2012). "For example, effective restoration of HACE1 expression in nephroblastoma by the addition of the specific DNA methylation inhibitor 5-azacytidine (5-Aza)." (PMID 40948788, 2025). "HECT domain and ankyrin repeat containing E3 ubiquitin protein ligase 1 (HACE1) was identified as a gene located in an affected region of chromosome 6q21 in human Wilms’ tumor." (PMID 27653971, 2016). "HACE1 expression is virtually undetectable in the SK-NEP-1 Wilms’ tumor cell line and in four of five additional primary Wilms’ tumor cases compared with patient-matched normal kidney." (PMID 34707697, 2012). "Furthermore, HACE1 demonstrates tumor-suppressive properties in Wilms' tumor 32, osteosarcoma 33, and colorectal cancer." (PMID 38706891, 2024). "For example, the altered expression levels of HACE1 leads toward the development of Wilms’ tumor." (PMID 36111624, 2022). "Since HACE1 is the target of epigenetic inactivation in Wilms’ tumor and has been proposed as a tumor suppressor gene in multiple human cancers, it is tempting to speculate that HACE1 might be involved in the pathogenesis of NKTCL." (PMID 34707697, 2012). "Moreover, HACE1 expression is virtually undetectable in the SK-NEP-1 Wilms’ tumor cell line and in four of five additional primary Wilms’ tumor cases compared with patient-matched normal kidney." (PMID 34707697, 2012).
lung carcinoma (9 papers, 2016 to 2025). "The expression of MBD3, a demethylation molecule, induced by propofol in a dose-dependent manner, promotes HACE1 protein expression and inhibits lung cancer cell proliferation by activating HACE1-OPTN axis autophagy." (PMID 40948788, 2025). "Prior reports suggesting HACE1-mediated RAC1 ubiquitination repressed the proliferation of breast and lung cancer cells further corroborate the notion that HACE1 suppresses ESCA progression through RAC1 ubiquitination 39-40." (PMID 38706891, 2024). "To investigate this process in vivo, we used a described previously mouse lung cancer model of Hace1 inactivation in which deletion of Rac1 and expression of oncogenic KRasG12D can be simultaneously induced by Adeno-Cre administration." (PMID 33603169, 2021). "In lung cancer, HACE1 ubiquitinates OPTN and targets it for autophagic degradation." (PMID 27213432, 2016). "The HACE1-OPTN axis synergistically suppresses the growth and tumorigenicity of lung cancer cells." (PMID 27213432, 2016).
liver cancer (5 papers, 2018 to 2025). An epithelial or non-epithelial malignant neoplasm that arises from the liver. "Demethylation of the HACE1 gene promoter has increased HACE1 expression, which inhibited liver cancer cell proliferation by activating OPTN-dependent selective autophagy." (PMID 40948788, 2025). "For instance, elevated methylation levels of the HACE1 gene have been observed in liver cancer cells; conversely, demethylation of the HACE1 promoter significantly curbs proliferation." (PMID 38706891, 2024). "HACE1 is frequently lost or downregulated in many tumors, including lung and liver cancers." (PMID 38660717, 2024). "Therefore, in addition to five TSPs, these studies identified the elevation of posttranslationally modified HACE1 in aggressive pediatric liver cancer." (PMID 30271949, 2018).
melanoma (5 papers, 2011 to 2024). A malignant, usually aggressive tumor composed of atypical, neoplastic melanocytes. "Notably, HACE1 was underexpressed or underwent allelic loss in cancer compared with respective normal tissues in glioblastoma, melanoma, lymphoma, lung and pancreatic cancers." (PMID 25659579, 2015). "In melanoma, even though expression levels of HACE1 are unchanged between nevi, primary, and metastatic melanoma, the loss of this E3 ligase impairs the migration of melanoma cells." (PMID 33800394, 2021). "The human tumor antigen PRAME (PRreferentially expressed Antigen in MElanoma) and HACE1 (HECT domain and Ankyrin repeat containing E3 ubiquitin-protein ligase) were both recently identified as a co-repressors of RAR signaling." (PMID 21949683, 2011). "However, a counterintuitive finding suggests that HACE1 might promote melanoma's lung metastasis." (PMID 38706891, 2024). "Recently, our group identified a new player in melanoma biology, the HECT domain and the ankyrin repeat-containing E3 ubiquitin-protein ligase 1 (HACE1)." (PMID 33800394, 2021).
osteosarcoma (5 papers, 2019 to 2025). A usually aggressive malignant bone-forming mesenchymal neoplasm, predominantly affecting adolescents and young adults. "Together, these data reveal reduced HACE1 expression in osteosarcoma, and point to a potential role for HACE1 loss in more aggressive osteosarcoma cells." (PMID 30622235, 2019). "HACE1-deficient osteosarcoma cells had elevated levels of active RAC1, which was associated with increased ROS levels." (PMID 30622235, 2019). "Decreased HACE1 expression in osteosarcoma clinical samples is associated with high-grade sarcoma and poor survival." (PMID 30622235, 2019). "Ectopic expression of HACE1 markedly inhibited anchorage-independent growth and cell motility of HACE1 osteosarcoma cell lines, and was associated with reduced RAC1 activation and decreased reactive oxygen species (ROS)." (PMID 30622235, 2019). "Based on publicly available databases, HACE1 expression is significantly downregulated in 76% of osteosarcomas, and this is associated with poor survival." (PMID 30622235, 2019). "Reduced HACE1 expression in osteosarcoma tumors was observed in 76% of cases and associated with high-grade lesions." (PMID 30622235, 2019). "For example, HACE1 loss may enhance ROS accumulation, thus contributing to genomic instability and tumor evolution in osteosarcoma." (PMID 30622235, 2019). "Therefore HACE1 downregulation was associated with high-grade osteosarcoma, further implicating HACE1 loss in osteosarcoma progression." (PMID 30622235, 2019). "HACE1 loss or silencing is implicated in tumor invasion and metastasis, and so we wondered whether HACE1 might influence osteosarcoma cell motility." (PMID 30622235, 2019). "This suggests that HACE1 loss is associated with osteosarcoma development." (PMID 30622235, 2019). "This suggests an unexplored link between HACE1 loss and osteosarcoma." (PMID 30622235, 2019). "In the current study, we hypothesized that HACE1 loss also contributes to osteosarcoma progression." (PMID 30622235, 2019). "Recently, HACE1 was described as a potential tumor suppressor gene in osteosarcoma, where it was found to inhibit growth, as well as invasive and metastatic capacity in vivo." (PMID 33603169, 2021). "Osteosarcoma cells engineered to express wt HACE1 showed markedly reduced soft agar colony formation and cell motility compared to those expressing ligase dead HACE1-C876S." (PMID 30622235, 2019). "Here we compared HACE1 expression in normal osteoblasts and osteosarcoma cell lines in vitro by western blotting and quantitative RT-PCR, and in human osteosarcoma specimens by immunohistochemistry." (PMID 30622235, 2019). "Taken together, these data show that HACE1 inhibits osteosarcoma cell motility and invasion in vitro." (PMID 30622235, 2019). "Compared to normal osteoblasts, both HACE1 protein and transcript levels were significantly reduced in a panel of osteosarcoma cell lines, pointing to transcriptional deregulation of HACE1 in osteosarcoma." (PMID 30622235, 2019). "In osteosarcoma clinical specimens, HACE1 protein expression was reduced in malignant cells compared to adjacent normal osteoblasts by IHC." (PMID 30622235, 2019). "HACE1 overexpression inhibited primary tumor growth of osteosarcoma xenografts in vivo, with significantly increased rates of necrosis and caspase-3 activation compared to tumors expressing vector alone or HACE1-C876S in vivo." (PMID 30622235, 2019). "Both HACE1 transcript and protein levels were reduced in osteosarcoma compared to osteoblasts in vitro." (PMID 30622235, 2019). "This suggests a transcriptional basis for reduced HACE1 expression in osteosarcoma compared to normal osteoblasts." (PMID 30622235, 2019). "To investigate potential links between HACE1 and osteosarcoma, we first analyzed publicly available databases for HACE1 mRNA expression in osteosarcoma samples (GSE33382) compared to mesenchymal stem cells (MSCs) (GSE28974)." (PMID 30622235, 2019).
osteosarcoma (continued). "HACE1 overexpression significantly downregulated both active RAC1 and ROS levels, pointing to a potential link between HACE1 loss and ROS regulation in osteosarcoma." (PMID 30622235, 2019). "Future work investigating the potential roles of HACE1 in osteoblast development and sequencing of the HACE1 locus in osteosarcoma specimens will be necessary to obtain a better understanding of the functions of this important protein in osteosarcoma." (PMID 30622235, 2019). "We next performed IHC to assess HACE1 expression in 25 formalin-fixed, paraffin-embedded osteosarcoma cases, selected for the presence of both malignant tissue and adjacent normal bone as an internal control." (PMID 30622235, 2019). "Together, these findings provide compelling evidence that HACE1 inhibits growth as well as invasive and metastatic capacity of osteosarcoma cells in vivo." (PMID 30622235, 2019). "Moreover, immunofluorescence showed strong staining for HACE1 in normal osteoblasts compared to MG63 osteosarcoma cells, further supporting HACE1 downregulation in osteosarcoma cells." (PMID 30622235, 2019). "HACE1 expression was significantly lower in osteosarcoma samples compared to MSCs." (PMID 30622235, 2019). "Here we demonstrate reduced expression of the 6q21 HACE1 tumor suppressor gene in osteosarcoma." (PMID 30622235, 2019). "Finally, we examined HACE1 expression in a publicly available osteosarcoma database linked to patient outcome (GSE21257), which revealed that lower HACE1 expression levels significantly correlates with poor overall survival (p-value = 4.2e−02)." (PMID 30622235, 2019). "Finally, HACE1 overexpression blocked osteosarcoma xenograft growth and dramatically reduced pulmonary metastases." (PMID 30622235, 2019). "Moreover, HACE1 expression in clonally derived pairs of high/low metastatic osteosarcoma cells showed an even further reduction in high compared to low metastatic cells." (PMID 30622235, 2019). "HACE1 inhibits growth, invasion, and metastasis of osteosarcoma cells in vitro and in vivo." (PMID 30622235, 2019). "In summary, these studies highlight HACE1 as a potential tumor suppressor in osteosarcoma." (PMID 30622235, 2019). "Most dramatically, ectopic of expression of wt HACE1 but not the ligase dead mutant led to complete loss of metastatic dissemination of osteosarcoma cells to spleen or lungs." (PMID 30622235, 2019). "Therefore, ectopic HACE1 expression reduces phenotypic transformation in osteosarcoma cells in vitro." (PMID 30622235, 2019). "The ability to reduce HIF1α levels provides a plausible mechanism for the anti-tumorigenic activity of HACE1, including potential roles in blocking metastasis, as it was recently shown that HACE1 overexpression completely eliminated detectable lung metastases of osteosarcoma cells in mice." (PMID 33603169, 2021). "Therefore, HACE1 tumor suppressor activity in osteosarcoma appears to require E3 ligase activity." (PMID 30622235, 2019). "Therefore, HACE1 may serve as a prognostic biomarker in osteosarcoma patients whereby low expression is predictive of poor overall survival." (PMID 30622235, 2019). "Therefore, HACE1 may serve as a useful prognostic biomarker in osteosarcoma." (PMID 30622235, 2019). "Together, these support a model whereby HACE1 downregulation results in enhanced RAC1 activation and ROS accumulation, contributing to osteosarcoma progression." (PMID 30622235, 2019). "In contrast, grade III osteosarcomas either showed only very weak staining or were completely negative for HACE1 immunoreactivity (panels ix–xii)." (PMID 30622235, 2019). "Moreover, wt but not ligase dead HACE1 dramatically reduced branching and invasive morphology of osteosarcoma cells in Matrigel." (PMID 30622235, 2019). "However, studies directly addressing the link between HACE1 and osteosarcoma are currently lacking." (PMID 30622235, 2019).
colorectal cancer (4 papers, 2012 to 2024). A primary or metastatic malignant neoplasm that affects the colon or rectum. "The aberrant methylation of HACE1 was frequently observed in colorectal cancer." (PMID 34707697, 2012). "Thus HACE1 might act as a tumor suppressor in colorectal carcinomas and HACE1 methylation might present a malignant potential in colorectal cancer." (PMID 34707697, 2012). "HACE1 is also downregulated in natural killer/T-cell lymphoma of the nasal type (NKTCL), colorectal cancer and gastric cancer." (PMID 34707697, 2012).
Huntington disease (4 papers, 2017 to 2025). Huntington disease (HD) is a rare neurodegenerative disorder of the central nervous system characterized by unwanted choreatic movements, behavioral and psychiatric disturbances and dementia. "Interestingly, recent in vivo data highlight the link between HACE1 and neurodegenerative diseases, since loss of HACE1 impacts Huntington disease-like phenotypes in a mouse model, and reduced levels of HACE1 were observed in patients." (PMID 29971063, 2018). "As a novel molecular target in neurodegenerative diseases, HACE1 is closely related to neurodegenerative diseases such as Alzheimer’s disease, Parkinson’s disease and Huntington’s disease." (PMID 40948788, 2025). "HACE1 expression provides neuroprotective response against toxicity generated by mutant huntingtin protein and interestingly HACE1 level was found to be decreased in Huntington’s disease patients striatum." (PMID 28579943, 2017).
neuroblastoma (4 papers, 2012 to 2024). Neuroblastoma (NB) is the most common solid, extracranial childhood tumor. "While HACE1 has been documented as a tumor suppressor in many cancers including neuroblastoma, the exact function of this gene and the associated variant have yet to be fully elucidated." (PMID 30200332, 2018). "In a genome-wide association study of 2817 neuroblastoma cases and 7473 controls, HACE1 and LIN28B were identified as two new associations at 6q16." (PMID 34707697, 2012). "In neuroblastomas, low HACE1 expression is associated with worse overall survival, suggesting that HACE1 may function as a tumor suppressor." (PMID 34707697, 2012). "While confirming the previous findings already described, the investigators identified new risk variants in HACE1 and LIN28B that were associated with the development of neuroblastoma." (PMID 30200332, 2018). "Authors found that five polymorphisms at the HACE1 gene and the LIN28B rs17065417 A>C polymorphism were associated with neuroblastoma susceptibility." (PMID 27021521, 2016). "Low HACE1 and high LIN28B expression in diagnostic primary neuroblastomas are associated with worse overall survival." (PMID 34707697, 2012).
Spastic paraplegia (4 papers, 2019 to 2024). Complete loss of the ability to move the lower limbs accompanied by spasticity of the lower limbs. "We aim to characterize the causality and molecular and functional underpinnings of HACE1 deficiency in a mouse model of a recessive neurodevelopmental syndrome called spastic paraplegia and psychomotor retardation with or without seizures (SPPRS)." (PMID 31321300, 2019). "Defects in HACE1 may cause spastic paraplegia and psychomotor retardation with or without seizures (SPPRS), an autosomal recessive complex neurodevelopmental disorder with onset in infancy." (PMID 38899231, 2024). "Spastic paraplegia and psychomotor retardation with or without seizures (SPPRS) is a neurodevelopmental disorder described so far in 26 patients of 14 unrelated families associated with autosomal recessive mutations throughout the HACE1 gene." (PMID 38899231, 2024). "Spastic paraplegia and psychomotor retardation with or without seizures (SPPRS) is a rare neurodevelopmental disorder associated with autosomal recessive mutations in the HACE1 gene." (PMID 38899231, 2024). "Mutations in HACE1 have been described in humans with a recessive neurodevelopmental syndrome called spastic paraplegia and psychomotor retardation with or without seizures (SPPRS) and HACE1 mutations in cancer samples have been associated with uncontrolled cell proliferation." (PMID 35061740, 2022). "After that, 3 cases of spastic paraplegia were found in patients (No. 2, 22, and 26) with responsible genes including (HACE1, ATL1, AP4M1), respectively, and two cases of cerebellar ataxia in patients (No. 14 and 43), whose responsible genes were SNX14, TDP2, respectively." (PMID 34540776, 2021).
esophageal cancer (3 papers, 2024 to 2025). A primary or metastatic malignant neoplasm involving the esophagus. "Silencing TRIP12 blocks the inhibitory effect of HACE1 on Rac1 protein degradation and esophageal cancer (ESCA) tumor growth." (PMID 40948788, 2025).